MUC15 (mucin 15, cell surface associated)
Diseases named in the same sentence as MUC15 in open-access papers (continued):
Sharing a sentence is not in itself a finding about the gene and the disease.
pancreatic cancer (2 papers, 2022 to 2025). "To characterize MUC15's role in metastasis within the pancreatic tumor microenvironment, we developed two complementary in vivo models." (PMID 41082352, 2025). "In in vivo pancreatic cancer models, modulating MUC15 levels controlled metastasis as predicted by the mathematical model." (PMID 41082352, 2025). "This study uncovers a size‐dependent adhesion paradigm, demonstrating that the glycocalyx protein MUC15 suppresses pancreatic cancer progression by attenuating integrin activation, focal adhesion assembly, and YAP mechanotransduction." (PMID 41082352, 2025). "Finally, these size‐dependent effects translated to in vivo outcomes, where MUC15 overexpression reduced metastasis and ECM remodeling in pancreatic cancer models." (PMID 41082352, 2025).
renal carcinoma (2 papers, 2017 to 2024). A carcinoma arising from the epithelium of the renal parenchyma or the renal pelvis. "Lastly, MUC15 and MUC20 methylation also appears to be of interest beyond renal carcinomas." (PMID 28978023, 2017).
cervical cancer (1 paper, 2021). A primary or metastatic malignant neoplasm involving the cervix. "The oncogene effect of miR-552 on cervical cancer cell proliferation and invasion was associated with its regulatory effect on its target gene MUC15." (PMID 34539882, 2021). "miR-552 expression was negatively associated with MUC15 expression in cervical cancer tissues." (PMID 34539882, 2021). "Compared with normal tissues, significant lower expression of MUC15 was detected in cervical cancer tissues." (PMID 34539882, 2021). "Reduced MUC15 expression was detected in cervical cancer, and MUC15 overexpression exhibited a tumor-suppressive effect." (PMID 34539882, 2021). "Functional assays revealed that MUC15 inhibited the proliferation and metastasis of cervical cancer cells." (PMID 34539882, 2021). "In concluding, our results highlighted the importance of miR-552 in promoting the proliferation and metastasis of cervical cancer cells via MUC15 pathway." (PMID 34539882, 2021). "The colony formation assay found that MUC15 overexpression cervical cancer cells formed less and smaller colonies." (PMID 34539882, 2021). "Conversely, miR-552 overexpression reduced MUC15 mRNA and protein expression in cervical cancer cells." (PMID 34539882, 2021). "As expected, MUC15 overexpression diminished the distinct growth capacity between miR-552 overexpression cervical cancer cells and control cells." (PMID 34539882, 2021). "Taken together, these data demonstrate that miR-552 acts as a potential oncogene miRNA in cervical cancer, which exerts its function through targeting MUC15." (PMID 34539882, 2021). "Collectively, our data demonstrated that MUC15 inhibited cervical cancer cells growth and metastasis." (PMID 34539882, 2021). "To elucidate the potential role of MUC15 in the progression of cervical cancer, we first checked its expression pattern in tumor tissues of cervical cancer by real-time PCR." (PMID 34539882, 2021). "Herein, we for first revealed that miR-552 promote cervical cancer proliferation and metastasis via directly regulating MUC15." (PMID 34539882, 2021). "MUC15 restoration partially abolished the discrepancy of growth and metastasis capacity between miR-552 overexpression cervical cancer cells and control cells." (PMID 34539882, 2021). "More importantly, MUC15 overexpression could abrogate the distinct growth capacity or metastasis ability between miR-552 overexpression cervical cancer cells and control cells." (PMID 34539882, 2021). "In this study, decreased MUC15 expression was detected in cervical cancer." (PMID 34539882, 2021). "MUC15 overexpression suppressed cervical cancer proliferation and metastasis." (PMID 34539882, 2021). "Moreover, cervical cancer cell lines in vitro also showed decreased MUC15 expression compared with normal H8 cervical epithelial cells." (PMID 34539882, 2021). "CCK8 assay showed that MUC15 overexpression suppressed cell growth in cervical cancer cells." (PMID 34539882, 2021). "Our data also showed that MUC15 was downregulated in cervical cancer tissues and cell lines." (PMID 34539882, 2021). "miR-552 knockdown increased MUC15 mRNA and protein expression in cervical cancer cells." (PMID 34539882, 2021). "Currently, the potential role of MUC15 in cervical cancer remains largely unknown." (PMID 34539882, 2021). "There was a significant negative correlation between miR-552 and MUC15 mRNA expression in human cervical cancer tissues." (PMID 34539882, 2021).
liver cirrhosis (1 paper, 2021). "The MUC15 rs10430847 variant genotypes were significantly associated with high capsule formation in nearly all subgroups in addition to subgroups of females, absence of liver cirrhosis, and presence of vascular invasion." (PMID 34007838, 2021).
Obesity (1 paper, 2020). Accumulation of substantial excess body fat. "These genes were also examined in female placentae, however, only Pi15, Nup210, Acta2, Rnf222, and Muc15 were significantly modulated by obesity." (PMID 32203108, 2020). "When comparing both timepoints, most transcripts exhibited a different expression pattern, including Muc15, Cnn1, and Acta2 which were not affected by obesity at E13." (PMID 32203108, 2020).
osteosarcoma (1 paper, 2021). A usually aggressive malignant bone-forming mesenchymal neoplasm, predominantly affecting adolescents and young adults. "MUC15 was found expressed significantly high in osteosarcoma tissues (p=0.0103)." (PMID 33391443, 2021).
thyroid (1 paper, 2018). "Either gain or loss of function study demonstrates that MUC15 is necessary and sufficient factor to induce feature of thyroid CSC." (PMID 30420637, 2018).
thyroid tumor (1 paper, 2018). A benign or malignant neoplasm affecting the thyroid gland. "Mostly thyroid tumors in patients have greater MUC15 expression than normal tissue, especially in higher-grade tumors." (PMID 30420637, 2018). "Thyroid tumors display greater MUC15 expression than neighboring normal thyroid epithelial cells." (PMID 30420637, 2018).
viral infection (1 paper, 2019). "The immunofluorescence co-staining of MUC15 and influenza viral hemagglutinin (HA) showed that MUC15 was tethered on the cell plasma membrane, and that viral infection significantly increased MUC15 expression." (PMID 31307416, 2019). "We also observed that expression of EGFR and phosphorylation of ERK1/2 were reduced at late phase of viral infection (such as 48 hpi, 72 hpi), in response to MUC15 increase." (PMID 31307416, 2019). "Besides, we also detected two main cellular signaling factors – EGFR and phosphorylated ERK1/2 (found as MUC15 targets), which could be stimulated in response to viral infection, and may induce downstream reactions such as anti-viral cytokine production." (PMID 31307416, 2019). "The main limitation in this study is that we could not ascertain the anti-inflammatory role of MUC15 during viral infection through the MUC15 knockdown experiments, because the hNECs derived from nasal biopsies were poorly transfected." (PMID 31307416, 2019). "While MUC15 did not interact with virus particles or reduce viral replication directly, positive correlations were observed between MUC15 and inflammatory factors in response to viral infection." (PMID 31307416, 2019).
cancer (25 papers, 2014 to 2025). A tumor composed of atypical neoplastic, often pleomorphic cells that invade other tissues. "Intriguingly, several genes showing positive correlation in gene bodies have been previously linked to cancer, including MUC15, HEPACAM2, CA10, NRG1 and RAB25 (Mitra, Cheng & Mills, 2012)." (PMID 32832275, 2020). "The few studies on MUC15 focused on its association with genesis of carcinoma." (PMID 31307416, 2019). "Integrating computational modeling and experimental validation, the work reveals a mechanical mechanism by which MUC15 constrains metastatic behavior, offering new insights into glycocalyx‐mediated cancer regulation." (PMID 41082352, 2025). "The dysregulation of MUC15 is observed in many cancers with links to EMT via EGFR inhibition, PI3K-Akt, and GSK3β/β-catenin signaling." (PMID 39483899, 2024). "Abnormal expression of MUC15 plays a crucial role in malignant tumors, affecting cell growth, adhesion, invasion and metastasis." (PMID 38021164, 2023). "MUC15 also has been shown as an oncogene in the development of cancer and influence cellular growth, adhesion, invasion, metastasis and immunosuppression." (PMID 33391443, 2021). "Recent studies demonstrated a potential role for MUC15 in the pathogenesis and metastasis of cancers." (PMID 34539882, 2021). "While a number of studies have reported that MUC15 is involved in cancer development and influences cellular growth, invasion, and metastasis as a tumor suppressor, no MUC15 polymorphism has been examined in tumor association studies." (PMID 34007838, 2021). "LRFN4, ADAMTS12, MCEMP1, HP and MUC15 are all cancer-related biomarkers, and all of them can also be used in judgment of cancer incidence in an independent manner." (PMID 32908454, 2020). "EMCN/MUC15 correlated genes were identified to be enriched in cancer-related processes, such as vasculature development, mitosis, and immunity." (PMID 32175327, 2020). "EMCN/MUC15 top 50 correlated genes were identified to be enriched in cancer-related processes, including vasculature development, mitosis, immunity, and so on." (PMID 32175327, 2020). "These indicate that genes correlated with EMCN and MUC15 in GC tend to be enriched in cancer related processes, such as vasculature development, mitosis, and immunity." (PMID 32175327, 2020). "To confirm cancer stem-like capacity driven by MUC15 in vivo, we additionally performed a tumorigenesis experiment using a xenograft mouse model." (PMID 30420637, 2018). "High cancer scores of MUC15 expression are significantly correlated with age, distant metastasis, and the presence of multifocality." (PMID 30420637, 2018). "MUC15 primarily shows a widespread decreased expression in cancers compared to normal, particularly strong in KIRC and KIRP, where the expression change ranges from −6.6 to −15.5-fold." (PMID 28978023, 2017). "MUC15 is an underexplored transmembrane glycoprotein, which has been shown to have various possible roles in cancers." (PMID 28978023, 2017). "Through GPCR-cAMP and integrin-FAK, MUC15 could activate MEK-ERK pathway so as to maintain cancer cell stemness and promote metastasis." (PMID 40225867, 2025). "To explore why the effects of MUC15 on cancer progression can be diametrically opposed to those of larger glycoproteins, we hypothesized that the glycoprotein size distribution determines the effect of the glycocalyx on integrin activation and dynamics." (PMID 41082352, 2025). "However, studies on the correlation between MUC15 and human disease mainly focus on malignant tumors, and its correlation with COPD is still poorly understood." (PMID 35513865, 2022). "These evidences indicate that it plays different roles in different types of cancers, which may because MUC15 involved in lots of biological functional regulations." (PMID 33391443, 2021). "Obviously, the role of MUC15 in cancer development is still confusing, and the expression and function of MUC15 in RCC are yet completely unknown." (PMID 32382053, 2020).
cancer (continued). "In particular, Muc15 is of interest to us as it is relatively unknown in the cancer biology of any tissue." (PMID 25380620, 2014). "The ability of MUC15 to remain within the kinetic trap, while maintaining lateral membrane mobility, suggests a size‐dependent regulatory mechanism by which glycoproteins differentially influence focal adhesion assembly and downstream signaling during cancer progression." (PMID 41082352, 2025). "However, the role of MUC15 in cancer is context-dependent and even opposite among different tumors." (PMID 38021164, 2023). "To further support the concept that Sox2 contributes to tumorigenesis and stemness in BC by upregulating these stem cell- or cancer cell-associated genes, we examined the oncogenic effects of Mucin-15 (Muc15), which has not been previously shown to be a Sox2 downstream target." (PMID 25380620, 2014). "Intermediate levels of smaller (<500 amino acids) glycoproteins such as MUC15 or MUC14 can switch a cell to a different adhesion state so as to inhibit cancer development." (PMID 41082352, 2025). "This mechanistic insight explains how MUC15, despite being a relatively small glycoprotein compared to mucins like MUC1, can significantly influence cancer cell behavior through size‐dependent physical interactions at the cell‐matrix interface." (PMID 41082352, 2025). "Consistent with this, we found MUC15 induces expression of several class of GPCR signaling related genes and confer properties of cancer stemness by the GPCR pathway." (PMID 30420637, 2018). "A recent study of mucin expression in a human epithelial carcinoma cell line (A549) showed a strong induction of MUC8, MUC15, MUC20, MUC21, and MUC22 mediated by RSV infection." (PMID 29162850, 2017). "We previously reported that the expression of several cancer stemness-related genes such as PROM1 (CD133), GPR49 (Lgr5) and MUC15 was significantly higher in RR cells as compared to RU cells derived from BC cell lines as well as primary tumor samples." (PMID 26683522, 2016). "Additionally, Mucin 15 (MUC15), which is downregulated in PCa, represents a potential therapeutic target by inhibiting EMT and cancer stemness through the GSK3β/β-catenin signaling pathway." (PMID 40556678, 2025). "Together, by mechanistic investigation of ascites pathophysiology, MUC15, and GPCR signaling, our study provides a fresh perspective on ascitic currents, the roles of the glycocalyx in cancer progression, and modalities of epithelial cell mechanosensing within high shear environments." (PMID 39483899, 2024). "For TCGA, the top genes were known cancer genes such as TTN, MUC15, and PTEN." (PMID 35053577, 2022). "However, MUC12, MUC15, MUC17, and MUC20 had a significant increase in methylation in only KIRP and KIRC, which goes against the overall observed demethylation of mucins in the cancers examined here." (PMID 28978023, 2017). "An increase in mucin promoter methylation was not commonly observed in cancers, yet in KIRP and KIRC, MUC15 promoter methylation increased strongly." (PMID 28978023, 2017). "However, the glycosylation differences of MUC15 and MUC20 between the cancer and normal cells were not fully explored." (PMID 36482940, 2022).
tumor (20 papers, 2014 to 2025). "This suggests the most significant loss of MUC15 occurs within the primary tumour between stages I and II, when ascites accumulation first begins rather than during peritoneal dissemination in the advanced stages of disease progression." (PMID 39483899, 2024). "Using both tail vein injection and syngeneic orthotopic transplantation models, we demonstrated that modulating MUC15 levels effectively regulated tumor metastasis and ECM remodeling, highlighting its potential as a therapeutic target for metastatic control." (PMID 41082352, 2025). "MUC15 is abnormally expressed in several tumors and plays both anti-tumor and promoting effects 12-14." (PMID 40225867, 2025). "In our orthotopic model, MUC15 overexpression significantly reduced tumor growth and ECM remodeling, as evidenced by Masson's staining and collagen fiber analysis." (PMID 41082352, 2025). "In patient-derived tumour samples, MUC15 expression was observed to decrease from stage I to stage II (0.60-fold change; P = 0.0299) and stage III (0.56-fold change; P = 0.0167)." (PMID 39483899, 2024). "The extracellular domain of MUC15 contains N- and O-glycosylated modifications, alterations in N-glycan had been shown to decrease FAK phosphorylation and were associated with tumor migration." (PMID 38021164, 2023). "To elucidate the tumor suppressor role of MUC15 in liver, we suppressed MUC15 in normal liver cell lines (HL7702 and THLE3)." (PMID 35236826, 2022). "In vivo limiting dilution assay revealed that overexpression of MUC15 significantly reduced tumor incidence and T-IC frequency." (PMID 35236826, 2022). "Earlier studies have suggested that TIPMs and MMPs were participated in MUC15-mediated tumor metastasis." (PMID 35236826, 2022). "In this study, we first demonstrated the high-expression of MUC15 in OS tumor cell lines and clinical samples." (PMID 33391443, 2021). "Then we further detected MUC15 expression in OS tumor cell lines and clinical samples to verify the results." (PMID 33391443, 2021). "We observed for the first time a patient subgroup that is characterized by a higher expression of MUC14/EMCN, MUC18/MCAM, and MUC15 in their tumor tissue." (PMID 33182511, 2020). "We observed a decrease in the expression of genes encoding membrane-bound MUC15 and secreted MUC7 and MUC19 in tumor samples (p < 0.01)." (PMID 33182511, 2020). "To verify the tumor-suppressive role of MUC15 in RCC in vivo, we established the tail-vein injection metastasis model using 786-O sublines in nude mice." (PMID 32382053, 2020). "The sustaining proliferation and activating metastasis are vital aspects of tumor progression, therefore, we aimed to explore these two important biological functions of MUC15 in RCC." (PMID 32382053, 2020). "In conclusion, we identified MUC15 could serve as a tumor suppressor gene and may become a promising candidate for individualized clinical diagnosis and treatment of ESCC." (PMID 40225867, 2025). "We finally found MUC15 protein was down-regulated in tumor tissues and it may play anti-tumor roles." (PMID 40225867, 2025). "To further validate the anti-tumor role of MUC15, we inoculated OE-MUC15 TE1 cells into nude mice." (PMID 40225867, 2025). "In our present results, MUC15 was down-regulated in ESCC tissues, and exogenous over-expression of MUC15 could significantly inhibite tumor cell proliferation, migration and invasion in TE1 and KYSE-150 cells in vitro." (PMID 40225867, 2025). "Thus, MUC15 influences not only tumor cell behavior but also stromal cell regulation and ECM remodeling." (PMID 41082352, 2025). "Meanwhile, the results of animal model also confirmed that over-expression of MUC15 could significantly restrict the growth of tumor cells in vivo." (PMID 40225867, 2025). "MUC15 was correlated with degree of tumor differentiation and could be a protective factor of survival." (PMID 40225867, 2025).